CYP2W1 (cytochrome P450 family 2 subfamily W member 1)
Diseases named in the same sentence as CYP2W1 in open-access papers (continued):
Sharing a sentence is not in itself a finding about the gene and the disease.
adrenocortical tumors (1 paper, 2014). "Furthermore, CYP2W1 immunoreactivity in adrenocortical tumors was associated with hormonal activity, with a more differentiated phenotype and in ACC with better response to mitotane therapy." (PMID 25144458, 2014). "A good correspondence between CYP2W1 mRNA expression levels and immunoreactivity was observed in the 25 adrenocortical tumor samples evaluated with both methods (P<0.001 by Chi-Square test per trend)." (PMID 25144458, 2014). "Adrenocortical tumors also showed a strong mean CYP2W1 expression (ACA = 0.024±0.027 and ACC = 0.018±0.023)." (PMID 25144458, 2014). "The CYP2W1 immunoreactivity in both benign and malignant adrenocortical tumors was similar to that in normal adrenal glands." (PMID 25144458, 2014). "In our adrenocortical tumors, CYP2W1 was expressed at higher levels in hormonally active tumors (steroid secreting) than in inactive tumors, suggesting a possible relationship between the CYP2W1 expression and the hormone production, which needs to be further evaluated." (PMID 25144458, 2014).
brain tumor (1 paper, 2025). "Overexpression of this specific gene set seems to be uniquely characteristic of PLAGL1/2-amplified tumors, as we do not find this combination, and especially not CYP2W1 expression, in any of the other investigated brain tumor types." (PMID 40751809, 2025).
breast tumors (1 paper, 2025). "Although less specific, the other orphan CYPs, such as CYP2W1, CYP2S1, CYP2U1, and CYP4X1, exhibit significantly higher expression in breast tumors compared to normal tissues." (PMID 41020804, 2025).
colon adenocarcinoma (1 paper, 2015). "Analysis of CYP2W1 expression in the colon adenocarcinoma cell line HCC2998 revealed that the gene expression can be induced by e.g. the antitumor agent imatinib, linoleic acid and its derivatives." (PMID 25844926, 2015). "The colon adenocarcinoma cell line HCC2998 used in this study seems to be an adequate model in that respect as it constitutively produces relatively high amounts of functional CYP2W1, the CYP2W1 levels are also increasing with the enhanced cell density." (PMID 25844926, 2015). "Scanning of a number of colon adenocarcinoma cell lines (results not shown) led to identification of the HCC2998 cell line (National Cancer Institute, Frederick, USA) with a significant level of CYP2W1 expression and activity." (PMID 25844926, 2015).
desmoid tumor (1 paper, 2025). A desmoid tumor (DT) is a benign, locally invasive soft tissue tumor associated with a high recurrence rate but with no metastatic potential. "Patient survival outcomes were analyzed based on CYP2W1 expression status, considering only malignant STS cases (n = 38) after excluding desmoid tumors from the analysis." (PMID 40136335, 2025). "In contrast, no CYP2W1 protein expression was detected in desmoid-type fibromatosis, a non-metastatic and well-differentiated subtype." (PMID 40136335, 2025). "Notably, the exclusion of desmoid tumors did not impact the distribution of CYP2W1-positive cases, as all desmoid tumors lacked CYP2W1 expression (0/4 cases)." (PMID 40136335, 2025). "Notably, no CYP2W1 expression was detected in desmoid-type fibromatosis (0%, 0/4)." (PMID 40136335, 2025).
gastric cancer (1 paper, 2020). A primary or metastatic malignant neoplasm involving the stomach. "Faint constitutive expression of CYP1A1 and CYP2W1 was detected in cytoplasm and nuclei of MNK‐45 gastric cancer cells." (PMID 31876059, 2020).
invasive breast carcinoma (1 paper, 2022). A carcinoma that infiltrates the breast parenchyma. "This study assessed CYP2S1 and CYP2W1 protein expression in a large independent cohort of early‐stage invasive breast cancer patients (Nottingham cohort) to evaluate associations with various clinicopathological and survival parameters." (PMID 35902379, 2022). "Protein expression of CYP2S1 and CYP2W1 was assessed in early‐stage invasive breast cancers (n = 1,426) using immunohistochemistry and correlated with various clinicopathological parameters and survival." (PMID 35902379, 2022).
leukaemia (1 paper, 2015). "However, an unpublished transcriptomic analysis of leukemia cells after imatinib treatment (Geo Dataset: GDS3044) also revealed induction of CYP2W1 in line with our data." (PMID 25844926, 2015).
pancreatic cancer (1 paper, 2024). "Incidentally, CYP2W1 is important for the activation and response to chemotherapy, such as mitotane in cancer, whereas high expression of CYP1B1 is known to drive gemcitabine resistance in pancreatic cancer." (PMID 39000545, 2024).
prostate adenocarcinoma (1 paper, 2019). "Nevertheless, it is possible to see that CYP2W1 is overexpressed in all cancers, except in prostate adenocarcinoma (PRAD)." (PMID 31258835, 2019).
rhabdomyosarcoma (1 paper, 2025). A rare aggressive malignant mesenchymal neoplasm arising from skeletal muscle. "Preliminary screenings by our group on mesenchymal tumors revealed CYP2W1 overexpression in a small subset of rhabdomyosarcomas, the most common pediatric STS subtype." (PMID 40136335, 2025). "In the current study, the highest expression frequencies of CYP2W1 protein expression were observed in synovial sarcoma (70%) and rhabdomyosarcoma (62.5%)." (PMID 40136335, 2025). "Synovial sarcoma and rhabdomyosarcoma subtypes exhibited the highest CYP2W1 protein expression, at 70% and 62.5%, respectively." (PMID 40136335, 2025). "An initial screening conducted by our group identified CYP2W1 upregulation in a subset of rhabdomyosarcoma tumors, the most common pediatric STS subtype." (PMID 40136335, 2025). "CYP2W1-based therapies could selectively target tumor cells, providing safer and more effective treatment options, especially for aggressive subtypes like synovial sarcoma and rhabdomyosarcoma." (PMID 40136335, 2025). "Additionally, they identify synovial sarcoma and rhabdomyosarcoma—particularly alveolar RMS—as key subtypes that could benefit from CYP2W1-targeted therapies in the future due to the frequent expression of CYP2W1 in these aggressive tumors." (PMID 40136335, 2025). "In summary, our research demonstrates that CYP2W1 is aberrantly expressed in a significant subset of primary STS tumors, with the highest prevalence rates in synovial sarcoma and rhabdomyosarcoma." (PMID 40136335, 2025). "Thus, if these results are validated in large and independent cohorts of pediatric patients, synovial sarcoma and rhabdomyosarcoma—particularly the alveolar subtype—could emerge as the most promising candidates for CYP2W1-based therapeutic strategies, given their notably high expression rates." (PMID 40136335, 2025). "Similarly, a high expression rate was observed in rhabdomyosarcoma (RMS), with 62.5% (5/8) of tumors expressing CYP2W1." (PMID 40136335, 2025).
synovial sarcoma (1 paper, 2025). "Synovial sarcoma exhibited the highest frequency of aberrant CYP2W1 expression, with 70% (7/10) of cases testing positive." (PMID 40136335, 2025).
tumor (21 papers, 2010 to 2025). "Significant associations were determined between CYP2W1 protein expression and histological grade and stage of the disease, both recognized markers of tumor progression." (PMID 40136335, 2025). "The expression of low CYP2W1 mRNA was significantly associated with tumour size ≥20 mm (χ2 = 6.919, df = 1, p = 0.009) and luminal A cancers (χ2 = 13.431, df = 5, p = 0.020)." (PMID 35902379, 2022). "Previous studies have shown that the tumor-specific expression of CYP2W1 in malignant tissues was associated with a loss in epigenetic control." (PMID 24699256, 2014). "CYP2W1 overexpression in tumor RMS was significantly associated with the age of the patients (P = 0.01) but not with any other parameter." (PMID 24699256, 2014). "Furthermore, CYP2W1 expression was significantly associated with higher histological grade, advanced tumor stage, and a trend toward reduced overall survival (p = 0.082)." (PMID 40136335, 2025). "An approach was proposed to use CYP2W1 as a new tumor-associated antigen for cancer immunotherapy." (PMID 33659048, 2021). "Interestingly, ribonucleotide reductase large subunit 1(RRM1) and cytochrome p450 2W1 (CYP2W1) expression levels has been associated with response to mitotane therapy and prolonged tumor-free survival." (PMID 33591997, 2021). "Tumor-specific expression of CYP2W1 has been suggested as an attractive target for CRC therapy exploiting either its ability to activate certain prodrugs to cytotoxic metabolites or using CYP2W1 as a new tumor-associated antigen for immunotherapy-based treatment." (PMID 25844926, 2015). "In this context, CYP2W1 has emerged as a promising therapeutic target due to its tumor-specific expression and unique metabolic properties." (PMID 40136335, 2025). "This suggests a strong correlation between mRNA abundance and protein translation efficiency, further underscoring the tumor-specific expression of CYP2W1 in pediatric STS tissues." (PMID 40136335, 2025). "Specifically, CYP2W1 was detected in 51.6% of high-grade tumors and 71.4% of Stage IV cases, suggesting a potential role for CYP2W1 in promoting tumor aggressiveness and progression in pediatric STSs." (PMID 40136335, 2025). "Among its members, CYP2W1 has emerged as a promising area of research due to its tumor-specific expression and aberrant reactivation in various human malignancies." (PMID 40136335, 2025). "High CYP2W1 expression was detected in 69% of tumor samples at the mRNA level and in 40.5% at the protein level, compared to absent or negligible expression in matched normal tissues (p < 0.001)." (PMID 40136335, 2025). "CYP2W1, having the ability to activate prodrugs, can increase the selectivity of chemotherapeutic agents to prevent tumor growth or metastasis as well as reduce the tumor volume before surgery." (PMID 41020804, 2025). "CYP2W1, a tumor-specific monooxygenase enzyme, has emerged as a promising therapeutic target due to its aberrant expression in various cancers." (PMID 40136335, 2025). "The mRNA level of CYP2W1 was determined by real-time quantitative RT-PCR assays in 42 paired pediatric STS tumor tissues and their corresponding adjacent normal tissues." (PMID 40136335, 2025). "To date, CYP2W1 stands out as the most tumor-specific member of the cytochrome P450 family identified in STS tumors." (PMID 40136335, 2025). "Both genes act as transcription factors for a regulatory subset of imprinted genes (IGs), components of the Wnt/β-Catenin pathway, and the potential drug targets RET and CYP2W1, which are also specifically overexpressed in this tumor type." (PMID 36437415, 2023). "CYP2W1 is a monooxygenase enzyme that has been shown to be expressed specifically in tumor tissues and during fetal life." (PMID 37948379, 2023). "In general, the difference in CYP2W1 expression between normal tissue and primary tumours was highly significant (P ≤ 0.0002)." (PMID 34556703, 2021).
tumor (continued). "Contrarily, CYP2W1 transcripts are mainly restricted to foetal and tumour tissues with minimal extrahepatic expression." (PMID 33809117, 2021). "For instance, CYP2W1, CYP1B1, CYP2C9, CYP2C8, CYP2J2, and CYP4A have been linked to tumor-specific expression." (PMID 31998435, 2020). "We previously showed that ACC patients having high CYP2W1 immunostaining at tumor level present a better response to mitotane therapy in comparison to those with low CYP2W1 staining." (PMID 32033200, 2020). "CYP2Ks share synteny with human CYP2W1, a tumor-specific CYP that oxidizes indole and chlorzoxazone." (PMID 29295707, 2018). "In order to verify the sensitivity of the antibody in the Western blot analysis used for the CYP2W1 protein, a series of dilutions of tumor sample Ca 29 were analyzed." (PMID 27598485, 2016). "As little as 0.78 μg protein from tumor Ca 29 resulted in a positive signal for CYP2W1, less than 1/30 of the amount of protein that was used for Western blot screening of the tumor and control samples." (PMID 27598485, 2016). "The sensitivity of the immunoblots allowed detection of at least 3% of the level in the high CYP2W1-expressing tumor." (PMID 27598485, 2016). "By Western blot analysis using the 852 antibody raised against the C-terminal of the CYP2W1 protein, only one tumor sample showed significant CYP2W1 protein levels (Ca 29)." (PMID 27598485, 2016). "One tumor sample only (Ca 29) displayed very high CYP2W1 mRNA expression, relative level 5.66 as compared to HepG2 cells." (PMID 27598485, 2016). "The imatinib mediated induction of CYP2W1 suggests an adjuvant therapy to treatment with duocarmycins that thus would involve induction of tumor CYP2W1 levels followed by the CYP2W1 activated duocarmycin prodrugs." (PMID 25844926, 2015). "Human cytochrome P450 2W1 (CYP2W1) is highly expressed in some cancers holding the potential to activate certain drugs into tumor cytotoxins." (PMID 25144458, 2014). "CYP2W1 in normal adjacent samples was only detected in one sample with Ct 35.7, while in the corresponding tumor samples CYP2W1 was expressed in Ct ranging from 29.4 to 36.0." (PMID 24699256, 2014). "In contrast, CYP2W1 mRNA was only detected in one non-tumor sample, obtained from a younger patient, whereas in the corresponding tumor samples, the CYP2W1 gene was expressed, and the positive rate was 61% (8/13)." (PMID 24699256, 2014). "Both CYP2E1 and CYP2W1 mRNA expression in the tumor samples were higher compared to normal matched samples between patients (P<0.02 and, P<0.01, respectively)." (PMID 24699256, 2014). "CYP2W1 mRNA was detected in tumor samples (8/13) and was only slightly expressed in one sample in normal tissue." (PMID 24699256, 2014). "At multivariate analysis including CYP2W1 levels, ENSAT tumor stage, and Ki67 proliferation index, the impact of CYP2W1 expression on both OS and TTP was statistically significant (HR = 3.9, P = 0.009 and HR = 4.9, P = 0.001, respectively)." (PMID 25144458, 2014). "Furthermore, efflux pumps (ABCB1, MRP1) and influx transporters (SLC7A11) significantly impact drug bioavailability, while age-dependent CYP metabolism and tumor-specific isoforms such as CYP2W1 represent metabolic vulnerabilities." (PMID 41425252, 2025). "Importantly, the prevalence of CYP2W1-positive cases and the levels of detectable CYP2W1 observed in our study also are comparable to those reported in some adult epithelial-origin malignancies, where CYP2W1 has shown tumor-selective expression." (PMID 40136335, 2025). "Interestingly, aberrant CYP2W1 protein expression was exclusively observed in STS tumor specimens with significantly elevated mRNA levels (≥5-fold increase compared to normal tissues)." (PMID 40136335, 2025).
tumor (continued). "Unlike CYP1B1 and CYP2E1—two other notable P450 enzymes that, while expressed in various cancers, including pediatric STSs, are also present in corresponding normal tissues—CYP2W1 appears to be exclusively upregulated in tumor tissues, making it a uniquely selective therapeutic target." (PMID 40136335, 2025). "This consistency suggests that CYP2W1’s tumor-specific reactivation and contribution to malignant behavior may represent a common feature among diverse cancer types, including pediatric STSs." (PMID 40136335, 2025). "Consequently, tumour-associated CYP450 isoforms, such as CYP1A1, CYP1B1, CYP2S1, and CYP2W1—have become a focus for the development of novel anticancer therapies." (PMID 41174467, 2025). "CYP2S1 and CYP2W1 expression was observed across all cores with staining intensity varying from weak to strong in both the cytoplasm and nucleus, and with heterogeneous expression observed between adjacent tumour cells." (PMID 35902379, 2022). "CYP2W1 demonstrates tumour‐specific expression, especially in epithelial tumours." (PMID 35902379, 2022). "Notably, the imatinib-induced expression of tumor CYP2W1 followed by activation of duocarmycin prodrugs was suggested as an adjuvant therapy of CRC." (PMID 33659048, 2021). "The positive correlation of the increasing CYP2W1 expression with tumor progression and metastasis in CRC could be used as a diagnostic tool." (PMID 33659048, 2021). "CYP2W1 has been identified in tumor-specific CYP24, particularly adrenal and gastric cancers." (PMID 31998435, 2020). "This might be explained either by tissue contamination from the high CYP2W1 protein expression in the tumor sample or by induction of expression by the tumor." (PMID 27598485, 2016). "At the same time cancer-specific expression and discovery of prodrugs metabolized by CYP2W1 to cytotoxins makes it an interesting target for cancer therapy and therefore a subject for intensive studies on its regulation and function in ontogeny and neoplasia." (PMID 25844926, 2015). "However, we were unable to validate our results on the nonpreamplified transcript or intratumoral protein levels because of the very low CYP2W1 expression in tumor tissues of the pretreatment set of patients." (PMID 25526449, 2014). "Furthermore, statistically significant associations were found between patient’s age and gene amplification for CYP2W1 in tumor samples." (PMID 24699256, 2014). "Interestingly, we found that among the 8 tumor samples that showed CYP2W1 expression, four corresponded to embryonal type." (PMID 24699256, 2014). "Current treatment options for ACC are still largely disappointing and the high expression of CYP2W1 in many ACCs indicates that CYP2W1 might become an intriguing target for tumor specific treatment." (PMID 25144458, 2014). "Human CYP2W1 is a tumor-specific CYP that oxidizes indole and chlorzoxazone, but not fatty acids." (PMID 21087487, 2010). "The presence of CYP2W1 in HNSCC further reinforces its potential functional role in cancerous cells, expanding its relevance beyond CRC, while CYP2S1 has been implicated in inflammatory responses, potentially contributing to the aggressive nature of HNSCC tumours." (PMID 41174467, 2025). "Therefore, identifying CYP2S1 and CYP2W1 expression in patient tumours may help in the selection of individuals that could potentially benefit from treatment with chemotherapeutic agents that require these enzymes for metabolism." (PMID 35902379, 2022). "However, the majority of tumour samples expressed CYP2W1 at a moderate (23%) to high (65%) level." (PMID 34556703, 2021). "In preclinical studies, CYP2W1 demonstrates the ability to selectively bioactivate prodrugs, such as duocarmycin analogs and AQ4N, into highly cytotoxic metabolites within tumor cells, thereby minimizing damage to normal tissues." (PMID 40136335, 2025).